BMP3 (bone morphogenetic protein 3)
Description:
Growth factor of the TGF-beta superfamily that plays an essential role in developmental process by inducing and patterning early skeletal formation and by negatively regulating bone density. Antagonizes the ability of certain osteogenic BMPs to induce osteoprogenitor differentiation and ossification. Initiates signaling cascades by associating with type II receptor ACVR2B to activate SMAD2-dependent and SMAD-independent signaling cascades including TAK1 and JNK pathways.
Synonyms: BMP-3A
Tractability: Antibody: UniProt places it where antibodies can reach, with medium confidence; UniProt predicts a signal peptide or a membrane-spanning region; its Gene Ontology location is reachable by antibodies, with medium confidence. PROTAC: its protein half-life has been measured.
Gene: Protein-coding gene on chromosome 4 (81,030,632 to 81,057,627, forward strand). Ensembl gene ENSG00000152785.
Subcellular location: Secreted
Gene Ontology:
Molecular function: BMP receptor binding; cytokine activity; signaling receptor binding; growth factor activity
Biological process: negative regulation of ossification; cell surface receptor protein serine/threonine kinase signaling pathway; cell-cell signaling; skeletal system development; osteoblast differentiation
Cellular component: extracellular exosome; extracellular region
Genetic constraint (gnomAD): Loss-of-function variants: 21 observed, 36.21 expected, observed/expected ratio (o/e) 0.58, 90% interval 0.41 to 0.83. The upper end of that interval is the gene's LOEUF score, 0.83, which puts it in group 3 of 6, group 1 being the genes least tolerant of losing a copy. Missense variants: 584 observed, 562.8 expected, observed/expected ratio (o/e) 1.04, 90% interval 0.97 to 1.11. Synonymous variants: 242 observed, 219.08 expected, observed/expected ratio (o/e) 1.1, 90% interval 0.99 to 1.23.
Homologues: Orthologues: chimpanzee BMP3 (98% identical), macaque BMP3 (96% identical), rabbit BMP3 (86% identical), dog BMP3 (86% identical), pig BMP3 (85% identical), guinea pig BMP3 (81% identical), rat Bmp3 (81% identical), mouse Bmp3 (80% identical), tropical clawed frog bmp3 (60% identical), zebrafish bmp3 (53% identical). Paralogues in human: GDF10 (42% identical), GDF5 (21% identical), BMP2 (21% identical), BMP4 (20% identical), BMP5 (19% identical), GDF6 (19% identical), BMP7 (18% identical), BMP6 (18% identical), GDF7 (18% identical), GDF2 (18% identical), BMP8A (17% identical), BMP8B (17% identical), and 19 more.
Diseases named in the same sentence as BMP3 in open-access papers:
BMP3 is named in the same sentence as 61 diseases in open-access papers, as found by Europe PMC text mining. Sharing a sentence is not in itself a finding about the gene and the disease. The quoted sentences say what the papers report.
colorectal cancer (22 papers, 2009 to 2025). A primary or metastatic malignant neoplasm that affects the colon or rectum. "BMP3, which is a type of bone morphogenetic protein, was initially reported in 2005 as one of the tumor suppression factors in colorectal cancer." (PMID 38681199, 2024). "While previous studies have examined the impact of polymorphisms within BMPs or their expression on colorectal cancer (CRC), only the BMP3 gene has been previously identified as hypermethylated in CRC tissue." (PMID 37628872, 2023). "One study in colorectal cancer reported that ACVR2B once bound to BMP3 thereafter resistant cell apoptosis via Smad-dependent signalling." (PMID 37333824, 2023). "In particular, BMP3 has been found to have promoter hypermethylated and therefore inactive in several cancers, especially including colorectal cancer (CRC)." (PMID 36262352, 2022). "BMP-3 promoter was hypermethylated in 5 samples and 4 of them were positive for colorectal cancer (sensitivity = 0.36 and specificity = 0.99)." (PMID 35345791, 2022). "For example, downregulation of BMP3 correlated with colorectal tumor progression, and re-introducing BMP3 in colorectal cancer cell lines significantly contributed to growth suppression." (PMID 36353620, 2022). "In the present systematic review, methylation of BMP3 was identified in 75% of plasma samples and 82% of tissue samples from patients with colorectal cancer." (PMID 33030559, 2021). "Downregulation of the BMP3 tumor suppressor gene is an early and frequent event in colorectal cancer." (PMID 33030559, 2021). "Cologuard (indicated for colorectal cancer screening) is a kit that includes a molecular analysis for DNA mutations (such as KRAS mutation), methylation biomarkers such as BMP3 and NDRG4 methylation, and an immunochemical assay for human hemoglobin." (PMID 33114412, 2020). "BMP3, which is an antagonist of osteogenic BMPs, inhibits the proliferation of colorectal cancer cells." (PMID 32568738, 2020). "BMP3 gene is often found hypermethylated and hence inactivated in several types of cancers including colorectal cancer (CRC), indicating that it has a suppressor role in carcinogenesis." (PMID 31665064, 2019). "In a multi-marker panel used for screening for colorectal cancer in stools, the high specificity of BMP3 complements other more sensitive methylated and mutant genes." (PMID 25077038, 2013). "BMP3 is also methylated in early stage colorectal cancers, and most importantly, in pre-cancerous tissue." (PMID 25077038, 2013). "Similar to our findings in biliary cancer cells, forced expression of BMP3 in colorectal cancer cell lines also suppressed cell proliferation." (PMID 25077038, 2013). "We confirmed the recently observed associations between DNA hypermethylation of BMP3 and MCC with CIMP+ and BRAFV600E in colorectal cancer." (PMID 20027224, 2009). "At the epigenomics level (methylation), an earlier study on colorectal cancer confirmed that the methylation alteration on BMP3 or BMP5 may trigger the malignant transformation of normal cells." (PMID 35155435, 2022). "Similarly, multi-target stool DNA tests involving methylation detection of NDRG4 in combination with BMP3 or SDC2 in the diagnosis of colorectal cancer have the sensitivities ranging from 85%-98% and specificity ranging from 86.6%-90% 32, 46-50." (PMID 33391430, 2021). "The aim of this study was to probe the methylation status of SEPT9, BMP3, NDRG4, and SDC2 in stool and study whether methylation of these genes is associated with colorectal cancer." (PMID 31602277, 2019). "DNA methylation biomarkers for colorectal cancer, such as SEPT9, NDRG4 and BMP3, which have received FDA approval for blood- or stool-based CRC screening, have been validated." (PMID 41291100, 2025). "For example, in the United States, hypermethylation in the promoter regions of BMP3, NDRG4, SEPT9, and VIM genes have been approved for colorectal cancer screening." (PMID 36831050, 2023).
colorectal cancer (continued). "BMP3, a member of the BMP family, has been shown to inhibit the proliferation of colorectal cancer cells and biliary cancer cells." (PMID 32568738, 2020). "The DNA methylation biomarkers BMP3 (bone morphogenetic protein 3), NDRG4 (N-myc downstream-regulated gene 4) and SDC2 (syndecan-2) has been extensively studied and are served as an alternative method in screening colorectal cancers and neoplasms 5, 16, 31, 35-44." (PMID 33391430, 2021). "In a study conducted in 2012, where 252 patients with colorectal cancer and 293 subjects with negative results from colonoscopy were screened, Cologuard (KRAS mutation + fecal hemoglobin + NDRG4 and BMP3 methylation) exhibited a sensitivity of 85% and specificity of 90%." (PMID 38681199, 2024).
adenoma (10 papers, 2017 to 2025). A neoplasm arising from the epithelium. "The sensitivity and specificity of fecal DNA multi-target testing, including KRAS mutation, BMP3, and NDRG4 methylation, for CRC and advanced adenoma was 80%, 91.2%, and the corresponding area under the curve was 0.856." (PMID 36905607, 2023). "Same as mutation markers, relative methylation level of Septin9, NDRG4, and BMP3 in CRC samples were higher than adenoma and NED groups, consistently in training and validation data sets." (PMID 33718241, 2021). "Accordingly, we found that BMP3 had considerably low positivity rates in all groups, while other markers had a high positive rate in those with malignant tumors and adenomas and had good specificity in those with polyps and control samples." (PMID 34621892, 2021). "Positive staining of BMP3 protein was observed in 27 out of 31 (87.10%) normal colon epithelial specimens, 28 out of 52 (53.85%) adenoma specimens, and 13 out of 37 (35.14%) CRC specimens." (PMID 31665064, 2019). "Cytoplasmic staining of BMP3 protein was significantly weaker in CRC tissues and moderately weaker in adenoma tissues than that in normal tissues." (PMID 31665064, 2019). "BMP3, NDRG4, and SDC2 showed a significantly higher methylation level in CRC than adenoma samples." (PMID 31602277, 2019). "One hundred and twenty colorectal samples (including 58 normal tissues, 46 adenomas, four Stage I CRC, eight Stage II CRC, and four Stage III CRC) were selected from the large sample set, and the methylation status of BMP3 and NDRG4 was determined by mass spectrometry." (PMID 29371978, 2017). "One was the panel consisting of methylated BMP3/NDRG4/VIM/TFPI2/mutant KRAS, β-actin, and Hb-level (and later refined and commercialized as Cologuard®), which in stool detected CRC with 87% sensitivity, adenoma with 82% sensitivity, and demonstrated a specificity of 93%." (PMID 33030559, 2021). "Furthermore, a 4-biomarker panel was the only one combining methylated BMP3, NDRG4, SDC2 with FOBT (and not FIT), achieving a moderately good performance for detection of CRC, 85.4% sensitivity and 92% specificity, and all adenomas (85.7% sensitivity)." (PMID 40402271, 2025).
pancreatic cancer (8 papers, 2012 to 2024). "Specifically, BMP3 (Bone Morphogenetic Protein 3) acts as a direct regulator of genes involved in apoptosis and cell cycle arrest in pancreatic cancer." (PMID 37481552, 2023). "We have also reported frequent BMP3 methylation in tissue and stool samples from patients with pancreatic cancers, even at early stage." (PMID 25077038, 2013). "After conducting a thorough analysis of published studies on cfDNA methylation in pancreatic cancer, as well as a comparative methylation analysis using the TCGA database, we have identified a set of consistently reported hypermethylated genes: BMP3, NPTX2, SFRP1, SPARC, and TFPI2." (PMID 37481552, 2023). "Meanwhile, the methylation status of NPTX2, BMP3 and SPARC genes plays an important role in the prognosis of pancreatic cancer." (PMID 39497722, 2024). "First, we have analyzed in cfDNA from eight mPDAC patients the methylation levels of five genes BMP3, NPTX2, SPARC, TFPI2 and SFRP1 known to be aberrantly methylated in pancreatic cancer." (PMID 37481552, 2023). "Of the three criteria, we identified eight genes that were the most highly/frequently methylated in pancreatic cancers (PCDH10, SPSB4, HOXA1, ADAMTS2, BMP3, C13orf18, CCND2, and SEMA5A)." (PMID 32520974, 2020). "Cell-free DNA hypermethylation of BMP3, MESTv2, SST, TFPI2, TAC1, ALX4, HIC1, SFRP2, SEPT9v2 and WNT5A has not previously been described in the literature in relation to pancreatic cancer." (PMID 27891190, 2016). "According to existing data, among the markers identified in the stool that may contribute to the early diagnosis of pancreatic cancer are the mutant KRAS gene and methylated BMP3." (PMID 33114412, 2020).
Obesity (6 papers, 2006 to 2025). Accumulation of substantial excess body fat. "BMP3 is also associated with overweight or obesity, as BMP3 expression in epididymal fat is substantially increased along with the development of high fat diet–induced obesity in 16-week-old mice." (PMID 33872596, 2021). "For example, the stress alarmone and anorectic protein Gdf15 interact with members of two other groups, including inflammatory Cx3cl1, axon guidance-related protein (Bmp3), and the obesity-related proteins Timp1 and erythropoietin (Epo)." (PMID 39329749, 2024). "BMP3 is associated with preadipocyte proliferation, FAM153A is a yet-to-be characterized protein of human adipocytes, and GRB7 is associated with human obesity." (PMID 38069028, 2023). "The results indicate that SFRP5, MEST, and BMP3, but not Naked1, are positively associated with the subsequent development of diet-induced obesity in 16 wk-old mice." (PMID 16733553, 2006). "Our analysis suggested significant enrichment (corrected P‐value < 0.01) in various catalogs, including obesity‐related traits (e.g., GMDS, PRKG1, and BMP2), Height (e.g., IGF2BP3, BMP2, and BMP3), and Body mass index (e.g., BMP2)." (PMID 40167159, 2025). "Similar to BMP2 and BMP3, BMP3B increased in the mesenteric adipose tissue of mice with diet-induced obesity." (PMID 33872596, 2021).
breast carcinoma (5 papers, 2012 to 2024). "SNHG3 lncRNA is responsible for bone metastasis in breast cancer through regulation of the miR-1273g-3p/BMP3 axis." (PMID 39695079, 2024). "The TGF– β family is involved in most of the considered diseases, e.g., TGFB1 in Osteoporosis, TGFB3 in Rheumatoid arthritis, Osteoarthritis and Multiple myeloma, TGFBR2 in HIV, Osteomyelitis and Measles, BMP in Breast cancer and Osteosarcoma, and BMP3 in Periodontitis." (PMID 30497370, 2018).
colorectal neoplasm (5 papers, 2013 to 2022). A benign or malignant neoplasm that affects the colon or rectum. "Previous studies observed CIMP-high and BRAF mutations in an early-stage colorectal neoplasm, and acquisition of BRAF mutation was considered to be mediated by DNA hypermethylation of several genes, including IGFBP7 and BMP3." (PMID 28623901, 2017). "We next compared the discriminatory power of these five new markers with two currently acknowledged robust methylation biomarkers for the early detection of colorectal tumors (BMP3 and NDRG4) in the same sample set." (PMID 29371978, 2017). "Similarly, our results showed that BMP3 expression was reduced when its gene promoter was hypermethylated in colorectal tumor tissues in addition to colon cancer cell lines." (PMID 31665064, 2019). "Also, BMP3 is often inactive during the early stages of most cases of CRC and is hypermethylated in most colorectal neoplasms." (PMID 31665064, 2019). "In colorectal neoplasms with methylation in the MLH1 promoter, bisulfite sequencing has demonstrated extensive hemi- or biallelic methylation of the BMP3 promoter; in these tissues silenced expression of BMP3 could be reversed by treatment with 5-Aza-dC and TSA." (PMID 25077038, 2013).
Brachycephaly (4 papers, 2017 to 2022). An abnormality of skull shape characterized by a decreased anterior-posterior diameter. "A missense mutation in BMP3 has been identified as a major contributor to brachycephaly, and a repeat expansion of the RUNX2 gene has been correlated with snout dorsiflexion and midface length in dogs." (PMID 36230363, 2022). "For example, a missense mutation in the gene Bmp3 (that encodes a growth factor, Bone morphogenetic protein 3) causes brachycephaly (shortened head) in domestic dogs." (PMID 29946416, 2018). "The results of these studies show association of brachycephaly with the RUNX2 gene on CFA12, SMOC2 on CFA1 and BMP3 on CFA32, chondrodysplasia with FGF4 retrogene on CFA12 and CFA18 and also with skull size." (PMID 36230363, 2022). "Examples of such variants include the brachycephaly associated SMOC2 and BMP3 variants and chondrodysplasia-associated FGF4 retrogenes on chromosomes 12 and 18, and there are likely more, yet undiscovered variants." (PMID 33599851, 2021). "Elsewhere, measurements and geometric morphometrics were used to quantify skull shape, revealing quantitative trait loci (QTL) associated with brachycephaly on CFA1, CFA5, CFA18, CFA30, and CFAX and a missense variant in the bone morphogenetic protein 3 (BMP3) gene on CFA32." (PMID 28552356, 2017).
colon cancer (4 papers, 2013 to 2021). "Cologuard©, Epi proColon©, and EarlyTect© are non-invasive screening tests for colon cancer that are currently in use and rely on the methylation of genes such as BMP3, NDRG4, SEPT9, SDC2 for early detection." (PMID 35663592, 2021). "Analyses of BMP3 function in colon cancer cell proliferation, migration, invasion, and apoptosis were performed using HCT116 and KM12 cells." (PMID 31665064, 2019). "BMP3 is a powerful stool biomarker for the screening and diagnosis of colon cancer, a disease in which BMP3 has an established tumor suppressor role." (PMID 25077038, 2013). "In studies of colon cancer cell lines, BMP3 was down-regulated by a methylation-dependent mechanism." (PMID 25077038, 2013). "BMP3 is one of two methylation markers (the other is NDRG4) included in the commercially available fecal Cologuard® test, approved by the FDA in 2014 as a colon cancer screening test." (PMID 33030559, 2021).
gastric cancer (4 papers, 2012 to 2023). A primary or metastatic malignant neoplasm involving the stomach. "Vitamin D, along with its receptor, is found to bind to these VDREs (p= <0.05), inhibiting BMP3 promoter methylation and increasing the expression of the TSGs in gastric cancer cells." (PMID 34722053, 2021). "Analysis of the RNA sequencing data of the TCGA‐STAD cohort showed that the expression of BMP3 in gastric cancer tissues is significantly decreased compared with normal tissue and its higher expression in the primary GC tumours is associated with poorer overall survival." (PMID 36779430, 2023). "In addition, through repressing methylation of BMP3 promoter, the role for 1,25-dihydroxyvitamin D3 in the progression of gastric cancer has been identified." (PMID 36262352, 2022).
myopia (4 papers, 2013 to 2025). "Polymorphisms at BMP3 have been previously reported to be associated with RE and myopia, retinal detachment, and ocular coloboma, a congenital disorder characterized by gaps in ocular tissues." (PMID 37351342, 2023).
osteoarthritis (3 papers, 2018 to 2020). A noninflammatory degenerative joint disease occurring chiefly in older persons, characterized by degeneration of the articular cartilage, hypertrophy of bone at the margins and changes in the synovial membrane. "To explore the role of BMP3 in RA, we collected synovial tissues from patients with osteoarthritis (OA) and RA." (PMID 32568738, 2020). "This strategy was applied successfully in dogs and permitted the identification of loci associated with osteoarthritis of hip joints, hip and elbow dysplasia, and related BMP3 (BONE MORPHOGENETIC PROTEIN 3) variations to skull diversity." (PMID 29566674, 2018).
osteoporosis (3 papers, 2013 to 2018). A condition of reduced bone mass, with decreased cortical thickness and a decrease in the number and size of the trabeculae of cancellous bone (but normal chemical composition), resulting in increased fracture incidence. "As such, the identification of a highly-conserved repressive element near the Bmp3 promoter could determine mechanisms to reduce Bmp3 expression in diseases of low bone mass such as osteopenia and osteoporosis." (PMID 23451274, 2013). "Thus, identifying the mechanism by which BMP3 acts to depress bone formation may allow for the development of new therapeutics useful in the treatment for osteopenia and osteoporosis." (PMID 29435407, 2018).
osteosarcoma (3 papers, 2013 to 2022). A usually aggressive malignant bone-forming mesenchymal neoplasm, predominantly affecting adolescents and young adults. "Functional characterization of various genomic fragments revealed the 0.8 kb region proximal to the annotated M. musculus Bmp3 transcription start site to be the minimal promoter in HEK293T cells, UMR-106 osteosarcoma cells, and primary calvarial osteoblasts." (PMID 23451274, 2013).